CXCL10 (C-X-C motif chemokine ligand 10)
Diseases named in the same sentence as CXCL10 in open-access papers (continued):
Sharing a sentence is not in itself a finding about the gene and the disease.
tumor (continued). "Conversely, according to other studies, PARP inhibition has been shown to induce cytosolic DNA accumulation and type I IFN response, along with increased intra-tumor CD8+T cell infiltration dependent on C-C chemokine ligand 5 (CCL5) and CXCL10 chemokines, irrespective of the BRCA mutational state." (PMID 36428727, 2022). "In contrast, CCL5, CXCL9, and CCL10 were upregulated in the low-risk group; high expression levels of CXCL9 and CXCL10 were correlated with improved OS in most tumors, and anti-PD1 therapy was not beneficial in CXCR3−/− (receptor of CXCL9 and CXCL10) tumor-bearing mice." (PMID 35795712, 2022). "Therefore, RORγt agonists may accelerate CCL20 production through signaling to Type 17 T cells to attract DC cells, resulting in an elevation of CXCL10 levels and immune CD8+ T cell infiltration in the tumor." (PMID 35459193, 2022). "We further observed other pro-inflammatory cytokines and chemokines [IFN-G, IP10 (also known as CXCL10), MCP-1 (also known as CCL2) and MIP2 (also known as CXCL2)] to significantly elevate, however, only in NR and 129R, the strains that showed the highest tumor growth." (PMID 36037073, 2022). "Interestingly, injection of recombinant IFN-γ beside the tumor was able to restore Cxcl9 but not Cxcl10 expression in B16-F10 tumors." (PMID 35103755, 2022). "Furthermore, in this study, we did not compare the expression CXCL10 protein separately in tumor cells and composites of tumor microenvironment." (PMID 34504204, 2021). "In contrast, N1 TANs produce chemokines, such as C-C motif chemokine ligand 3 (CCL3, CXCL9, CXCL10), to recruit CD8+ T cells to TME and secrete cytokines (e.g., IL-12, TNF-α, and GM-CSF) to activatethe cytotoxicity of CD8+ T cells, thus providing anti-tumor effect." (PMID 34359674, 2021). "For the activation of immune cells with MMP inhibition by MMST, CXCL-10 stimulated immune cells through polarization and activation of Type 1 T-helper cells, resulting in the enhanced paracrine secretion of IFN-γ and IL-2 to facilitate the anti-tumor efficacy of TMNPs + HT." (PMID 34959271, 2021). "Moreover, CXCL10 was not significantly related to T stage (P > .05), but it was related to tumor stages, N stage and M stage (P < .05)." (PMID 34559115, 2021). "CXCL10 is one of the most important inflammatory CXC chemokines and is involved in many physiological and pathological processes such as angiogenesis, chronic inflammation, immune dysfunction, tumour development and dissemination, in which ACKR2 has also been shown to play critical roles." (PMID 33801414, 2021). "MSI tumor samples displayed a peculiar cytokine profile compared to MSS tumors overexpressingchemokine (c-c motif) ligand (CCL-) 5, chemokine (C-X-C motif) ligand (CXCL-) -8, CXCL9, interleukin (IL-)-1β, CXCL10, IL-16, growth-regulated protein α (GROα), and IL-1 receptor agonist (IL1-ra)." (PMID 34072037, 2021). "The gene expression of multiple inflammatory markers in the heart was significantly upregulated in tumor-bearing mice as compared to tumor-free mice, including the pro-inflammatory cytokines IL-1α, IL-1β, IL-6, and TNF- α and the inflammatory chemokines Mcp-1, Cxcl1, and Cxcl10." (PMID 34445729, 2021). "The M1 macrophages produce pro-inflammatory factors (TNF-α, IL-1β, and iNOS), chemokines (CXCL10, CXCL11, and CCL2), antigen-presenting molecules such as MHCII, costimulatory molecules (CD86 and CD80), and antigen-treated peptidases, which play an anti-tumor role in cancer." (PMID 34034714, 2021). "Therefore, upregulation of GM-CSF, CXCL10, and CCL2 in response to miR-200c restoration may break a vicious paracrine loop between BC cells and macrophages known to support tumor progression." (PMID 34045467, 2021). "In addition, CXCL10 and CXCL11 were closely related to CD8+ tumor-infiltrating lymphocytes, which may predict benefit from PD-1 blockade therapy." (PMID 34093667, 2021).
tumor (continued). "Other chemokines upregulated in either the tumour or infiltrating immune cells by CHK1i+LDHU, including CCL5 that directly recruits Tregs or CXCL9, CXCL10, CXCL11 that recruit activated effector, T, NK and NKT cells, as well as Tregs, may also be responsible for the accumulation of Tregs." (PMID 34359633, 2021). "Moreover, we identified the IFNγ-CXCL10 axis as being one of the drivers of TCB-mediated T cell infiltration in tumors, whereby IFNγ released by activated T cells induces CXCL10 secretion, which in turns attracts CXCR3-expressing T cells into the tumor sites." (PMID 33406104, 2021). "Therefore, IL-18 and IP-10/CXCL10 in NPC may play dual roles in the recruitment and suppression of CXCR3+ tumor infiltrating NK cells and T cells." (PMID 33718235, 2021). "NPC patients with elevated levels of CXCL10 have also been observed to have poorer prognosis, suggesting that despite their pro-inflammatory role, CXCL10 and IL-18 are unlikely to result in tumour-suppressive effects." (PMID 34956172, 2021). "Importantly, some of the cytokines and chemokines upregulated in the tumor were also elevated in the plasma of mice receiving heterologous KV vaccine, including increased levels of IFN-γ, CCL5, CXCL10, CCL2, IL-6, CXCL1, and IL-1β one day after VSV-GP-HPV boost." (PMID 34465781, 2021). "In addition, there was a trend for a positive correlation of IL-8 and IP-10/CXCL10 with perivascular CD163+ cell infiltrates as well as a trend for a positive correlation of the percentage of CD163+ cells and MDC-1/CCL22 in the tumor core." (PMID 34654395, 2021). "In addition, the deficiency of MettL3 or Mettl14 in tumors results in enhancing cytotoxic tumor-infiltrating CD8+ T cells, and increasing the secretion of IFN-c, Cxcl9 and Cxcl10 in TME in vivo, which proves that the immune system and tumor microenvironment have metastasized in tumor m6A mRNA." (PMID 35069586, 2021). "Although this mechanism contributes to the suppression of tumor progression, it may be offset by the inhibition of the angiostatic cytokines CXCL9, CXCL10, and CXCL11; this can promote, in addition to tumor neovascularization, tumor growth or metastasis formation." (PMID 34442627, 2021). "CAF with tumor-promoting functions secrete growth factors (HGF, IGF1, CTGF, PDGF, VEGF, LIF), cytokines (IL-1, IL-4, IL-6, IL-8, IL-10, TGF-β), and chemokines (CCL2, CCL5, CXCL5, CXCL9, CXCL10, CXCL12), WNT5α, and bone morphogenic protein 4 (BMP4), which promote tumor progression." (PMID 35008832, 2021). "In addition, SHP2 inhibition increased expression of CXCR3 ligands, CXCL9 and CXCL10, in MIA PaCa-2-PBMCs co-culture, suggesting that upregulation of chemoattractant cytokines by inhibition of SHP2 may be a common phenotype in the tumor microenvironment." (PMID 33446805, 2021). "In addition, we examined the CXCL10 expression profiles across all tumor samples and paired normal tissues." (PMID 33240622, 2020). "As CXCL9 and CXCL10 shares same receptor CXCR3 in T lymphocytes, we would like to understand whether the CXCL9 has similar or opposite function with CXCL10 in regulating tumour microenvironment." (PMID 31913856, 2020). "Cytokine profiling of conditioned media from the co-culture of 3-D MVNs with tumor spheroids revealed a cooperative production of multiple chemo-attractants downstream of STING such as CXCL10, CCL5, and CCL2, which was surprisingly independent of cancer cell STING." (PMID 33013881, 2020). "In addition, levels of chemokines (CXCL10, CCL5, IFN-β) were lower in SKIL-overexpressed tumor compared to control, and further TAZ silencing significantly increased chemokine levels in those SKIL-overexpressed tumor." (PMID 33268765, 2020). "In addition, the expression of CXCL9, CXCL10, and CXCL11 was significantly correlated with the presence of tumor-infiltrating cytotoxic CD8+ T cells and CD4+ TH1 effector cells, which represent an independent positive predictor of prolonged disease-free survival of CRC patients." (PMID 33419310, 2020).
tumor (continued). "A recent review reports that the CXCL9/CXCL10/CXCL11/CXCR3 axis is responsible for angiogenesis inhibition, and the activation and migration of immune cells such as cytotoxic lymphocytes and natural killer cells into the tumor microenvironment, to prevent tumor progression in BCa." (PMID 33003392, 2020). "We observed that CXCL10 and ADAM10 had negative associations with tumor purity." (PMID 32206083, 2020). "Thus, phosphorylated TBK1 (pTBK1) and production of specific cytokines downstream of IRF3, such as CXCL10, can be measured as a function of STING activation, which plays important roles in tumor cells, antigen presenting cells, and potentially other cell types." (PMID 33013881, 2020). "Notably, tumor cells expressed relatively high levels of chemokines (e.g., CCL20, CCL19, and CXCL10), while the corresponding receptors were widely expressed in immune cells, suggesting that these chemokines play significant roles in enhancing immune cell infiltration into NPC tumor tissue." (PMID 32686767, 2020). "In addition, we measured protein concentration in the whole tumor tissue (used in the PK experiments) by ELISA and found that CXCL10 showed a non-significant trend for increase after treatment with intermediate dose regorafenib and anti-PD1 antibody (n=4)." (PMID 33234602, 2020). "On performing a microarray analysis of cytokines, chemokines, and receptors, we found that, among others, CXCL10 was up-regulated in Tα1-DC as compared with GM-DC and FL-DC, whereas CCL22 was apparently down-regulated, consistent with the results obtained at the tumor site." (PMID 32817121, 2020). "CXCL9, CXCL10, and CXCL11 were found to recruit CD4+ and CD8+ lymphocytes, while CXCL13 could specifically attract T regulatory and Th2 lymphocytes into the tumour microenvironment." (PMID 31913856, 2020). "However, some studies also indicated that these chemokines might play tumorigenic roles by promoting tumor metastasis and proliferation; thus, the specific roles of CXCL9 and CXCL10 in PC remain unclear." (PMID 33363572, 2020). "The increased production of IFN-γ by intratumoral lymphocytes could enhance the intratumoral expression of CXCL9 and CXCL10 and subsequent recruitment of the hetIL-15-expanded pool of circulating CXCR3+ lymphocytes, generating a positive amplification loop that limits tumor growth." (PMID 32461349, 2020). "Importantly, we also observed that cancer cell cGAS deletion significantly decreased expression of both CXCL10 and IFN-β in co-cultured HUVECs, providing direct evidence that ablation of 2′3′-cGAMP export from tumor cells suppresses STING signaling in endothelial cells." (PMID 33013881, 2020). "For example, CXCL9 and CXCL10 induce effector Th1/Th17 cells and CXCL11 drives a Treg and Th2-biased effector cell polarization upon activation of CXCR3 on CD4+ T cells, while they upregulate tumor cell-related proteins that are beneficial for their survival, such as PD-L1." (PMID 31216755, 2019). "However, DOC didn’t influence the levels of CXCL10 and CXCL9 in tumor cells." (PMID 30744691, 2019). "Also notable is a minimal change in expression of the chemokine CXCR3 but a significant increase in the expression of its ligands, CXCL10 and CXCL11, which are important in activating other signaling molecules that recruit immune cells for the general enhancement of anti-tumor pathways." (PMID 31795829, 2019). "On the one hand, the CXCR3 chemokines, especially CXCL9 and CXCL10, facilitate the recruitment of CXCR3-positive Th1, NK, and NKT cells as well as cytotoxic T lymphocytes to the tumor microenvironment, which trigger the development of a tumor-suppressive immune milieu." (PMID 31482487, 2019). "However, co-treatment of CT26 or LL/2 tumor-bearing mice by cisplatin with CXCL10 is required to have more important tumor growth inhibition, suggesting that CXCL10 alone is not enough." (PMID 31861811, 2019).
tumor (continued). "Moreover, blockade of IL-4 resulted in overexpression of pro-inflammatory cytokines (CXCL10, IL-1β, IL-15, IL-10 and IL-6) and lower expression of immunosuppressive molecules (Foxo3, IDO1 and PD-L1) as compared to cryo-thermal eosinophils + tumour-bearing DCs group." (PMID 31519961, 2019). "As expected, the tumor-bearing DCs co-cultured with cryo-thermal macrophages were highly matured, as demonstrated by the increased percentage of CD11c+CD86+MHC II+ DCs along with the higher relative expression of IL-6, TNF-α, CXCL10, IL-1β, IL-12p40, and IL-15 mRNA." (PMID 30833570, 2019). "CXCL10 is produced in greater concentrations in pleural fluid compared to the supernatant of primary cells, suggesting additional origins of the chemokine rather than solely from tumor cells." (PMID 31867277, 2019). "Due to the high expression of CXCR3-B on endothelial cells and the angiostatic effect of CXCL10, CXCL9, and CXCL4, it was proposed that the CXCR3-B variant could be responsible for this negative impact on tumor angiogenesis." (PMID 31216755, 2019). "Further study in mouse model demonstrated that downregulated cGAS-STING pathway led to decreased tumor-infiltrating CD3+ CD8+ T cells by reducing the expression of downstream genes of type I IFN such as chemokine (C-X-C motif) ligands 9 and 10 (CXCL9 and CXCL10)." (PMID 30935414, 2019). "CXCL10 is expressed in OC TAMs as well as in peritoneal macrophages from tumor-free patients, while IL2 is not a transcribed gene in macrophages and hence is devoid of active marks but apparently harbors H3K4me3- and H3K4me1-modified nucleosomes within 2,000 bp of its TSS." (PMID 29997615, 2018). "Th-1 lymphocytes recruited to a tumor site may be responsible for enhanced production of IFN-γ and tumor necrosis factor-α (TNF-α) which in turn stimulates CXCL10 secretion from a variety of cells helping to maintain and potentiate cytokine production in the tumor microenvironment." (PMID 29416784, 2018). "In addition, poly(I:C) induced higher levels of proinflammatory cytokine secretion (IFN-I, IL-6, and CXCL-10), MHC I expression of tumor cells, and monocyte activation in vitro, impairing tumor growth in vitro and in vivo even when TLR signalling was hampered on host cells." (PMID 29854832, 2018). "As a result, TILs highly expressing CXCR3, which is the receptor for CXCL9 and CXCL10, could not be recruited to the tumor site." (PMID 30064449, 2018). "To evaluate changes in the tumor microenvironment induced by RT53 injection that could explain the increased number of T lymphocytes, we used real-time RT-PCR of tumor extracts to analyze the relative expression of the pro-inflammatory chemokine ligands CCL2 and CXCL10." (PMID 30080874, 2018). "qPCR revealed that the triple treatment resulted in the highest expression of mRNA for the T cell specific chemokines CXCL9 and CXCL10 in tumors, suggesting that these two chemokines might be responsible for the enhanced infiltration of CD4+ and CD8+ T cells in the tumor tissues after treatment." (PMID 28881713, 2017). "CXCL10 induces a wide spectrum of physiological and pathological effects including chemotaxis, induction of apoptosis, regulation of cell growth and mediation of angiostatic effects via the CXCR3 receptor, resulting in immune dysfunction, tumor development, metastasis and dissemination." (PMID 28445977, 2017). "An unfortunate effect could then be that CXCL8 and CXCL10 display pro-tumor activity in the absence of tumor-inhibiting type I IFNs." (PMID 28717003, 2017). "Tumor upregulated chemokines included the followings: CXCL5 (138 fold increase); CCL25 (70 fold increase); CXCL11 (26 fold increase); CXCL6 (20 fold increase); CXCL1 and CXCL10 (11 fold increase); CXCL3 (8 fold increase); and CXCL9, CXCL2, and CCL3L1 (6 fold increase)." (PMID 29088818, 2017).
tumor (continued). "Upon tumour antigen pulsing, high levels of chemokines that sustain the recruitment of circulating DCs to inflamed tissues, such as CCL3, CCL4, were expressed, whereas at late time-points constitutive lymphoid chemokine such as CCL2, CCL8, CXCL10, CXCL12 and RANTES were selectively up-regulated." (PMID 26795765, 2016). "In our study, CCL5 and CXCL10 were more highly expressed in cancerous tissues than in marginal sites; the chemokines' expression was not affected by patients' age, gender, tumor differentiation, or clinical TNM stages, except that CCL5 was further upregulated in clinical T3-T4 stages." (PMID 26317795, 2015). "Thus, the higher induction of CXCL10, CCL4 and GMCSF mRNA exhibited by the good responder group was not unexpected and suggests that these patients may have greater anti-tumour immunity." (PMID 26115406, 2015). "Thus, CXCL9, CXCL10, CXCL16, CCL5, and CX3CL1 can be used to efficiently mobilize CTLs from regional lymph nodes to tumor tissues with an objective to enhance CTL-mediated tumor destruction." (PMID 24966464, 2014). "Moreover, CXCL10 and VEGF also play important role in tumor angiogenesis." (PMID 22384233, 2012). "CXCR3, which is present on activated MO/MAs and on activated T cells, binds several rIFN-γ1b- induceable chemokines, including CXCL9/Mig, CXCL10/IP-10, and CXCL11/I-TAC These chemokines might facilitate recruitment of activated leukocyte subsets to the tumor site." (PMID 16603073, 2006). "However, in an admix tumour, the lack of CXCL10 expression by IFNγRKO tumours might contribute to T cells preferentially targeting and killing WT tumours." (PMID 39746898, 2025). "Interestingly, the activation of the CXCL10/CXCL11–CXCR3 axis and TLR3/TLR4 signaling pathways suggested that the combination of hyperthermia and radiotherapy could effectively reshape the tumor immune microenvironment and enhance tumor cell sensitivity to cytotoxic attacks." (PMID 41280655, 2025). "In addition, the IT L1 peptide/polyI:C-treated mice displayed an increase in CXCL10, CCL2, CCL3 and CCL4 and GM-CSF in the tumor lysate which could be involved in the recruitment, retention and maturation of myeloid and lymphoid cells in the tumor." (PMID 40280970, 2025). "Therefore, they cannot respond to the CXCL10 signal and are not recruited to the tumor site." (PMID 41463372, 2025). "In our study, CB-839 alone did not induce CXCL10 in cancer cells but selectively impaired the growth of MTAP-deficient cancer cells and restored CXCL10 expression under immune co-culture, suggesting a dual mechanism involving both tumor cell-intrinsic cytotoxicity and immune cell-mediated feedback." (PMID 41246302, 2025). "APC-derived CXCL10 throughout the tumor core can promote widespread T-cell infiltration and effective tumor cell killing, whereas production confined to the tumor periphery typically results in a localized, non-infiltrating immune response that fails to control the tumor." (PMID 41516196, 2025). "Higher levels of circulating CXCL10 in non-responding patients may reflect pro-tumor activity." (PMID 38236249, 2024). "Moreover, CXCR3, which is the corresponding receptor of Cxcl9 and Cxcl10, is expressed by stem-like CD8+ Tpex cells and functions in CD8+ T-cell migration and positioning within tumors, as reported by prior studies, was significantly upregulated in CD8+ T cells after LDRT treatment of tumor." (PMID 38001101, 2023). "Furthermore, the in vitro co-culture assays revealed a significant upregulation of CXCL10 in bone marrow-dendritic cells (BMDCs) and bone marrow-derived macrophages (BMDMs) when co-cultured with LDRT-treated tumor cells, compared to those co-cultured with untreated tumor cells." (PMID 38001101, 2023). "Quantitative PCR (qPCR) confirmed a significant increase of mRNA expression for the chemokine ligands Cxcl10 and Cxcl11, supporting our hypothesis that PARP14 inhibition enhances IFNγ signalling in tumour cells and upregulates immune cell infiltration into tumours." (PMID 37752135, 2023).